DRD4 (dopamine receptor D4)
Diseases named in the same sentence as DRD4 in open-access papers (continued):
Sharing a sentence is not in itself a finding about the gene and the disease.
tumor (15 papers, 2018 to 2025). "Liu and colleagues have found that, through DRD4 stimulation, dopamine dampens the acquisition of the M2 phenotype by tumour-associated macrophages, a subset of macrophages that support tumour development." (PMID 36428964, 2022). "Specifically, high DRD4 expression in tumor samples of the GSE131521 dataset could be associated with the particular properties of these samples because all of them were collected from patients with metastatic brain damages." (PMID 35053262, 2022). "DA influences tumor behavior via its receptors, categorized as D1-like (DRD1, DRD5) and D2-like (DRD2, DRD3, DRD4), which vary in tumor expression and function." (PMID 40456735, 2025). "In parallel, a series of experimental analyses showed that MYH9 and DRD4 contributed to malignant tumor behavior, and these results suggested that MYH9 and DRD4 have potential as therapeutic targets in CC." (PMID 36345155, 2023). "DRD4 is a member of the dopamine receptor family and involved in the positive regulation of tumor behaviors, such as tumor cell proliferation, invasion and metastasis." (PMID 34316400, 2021). "Moreover, DRD4 expression increased progressively from tumor‐node‐metastasis (TNM) stage I to stage IV in CRC." (PMID 39679842, 2025). "The DRD2 inverse agonist and antipsychotic haloperidol improved the efficacy of an epidermal growth factor receptor inhibitor, although haloperidol (which also has efficacy in the nanomolar range on DRD3, DRD4, and several other receptors) was insufficient to decrease tumor growth alone." (PMID 33945569, 2021). "Based on tumor stage features and the expression of the three identified candidate genes, RABGAP1L, MYH9, and DRD4, we developed logistic regression models for the prediction of CRC patient prognosis by ML." (PMID 36345155, 2023). "Further studies reported that in neural stem cells dopamine receptor D4 (DRD4) antagonists inhibit GBM growth, induce G0/G1 arrest and promote tumour cell differentiation and apoptosis in vitro." (PMID 35393545, 2022). "Regarding membrane receptor gene expression, we found that SSTR1, DRD4 and DRD5 expression was higher in responder tumours at both three and six months after treatment." (PMID 29266696, 2018). "DRD4, a key dopamine receptor, relays light–dark signals in the retina to synchronise intracellular clocks; in CRC, aberrant DRD4 up-regulation activates the TGF-β pathway, enhancing tumour migration and invasion." (PMID 41174721, 2025). "Comparison of expression profiles of ET (≤40 years) and LT (≥55 years) yielded few genes that are unique between the two groups, 7 genes B4GALNT1, S100P, KLK4, HIST3H2A, DRD4, PCSK1N, and BAPX1 were significantly overexpressed in early-onset tumours compared to late-onset tumours." (PMID 31292488, 2019). "Both DRD2 and DRD4 have significantly higher expression in the non-tumor samples than the GBM samples, while DRD3 has similar expression between GBM and non-tumor." (PMID 33945569, 2021).
cancer (12 papers, 2016 to 2025). A tumor composed of atypical neoplastic, often pleomorphic cells that invade other tissues. "DRD4 belongs to dopamine receptor (DR) family that is associated with the progressive phenotypes of cancer." (PMID 37377935, 2023). "Intriguingly, DRD4 and GRB2 were two mostly shared genes mediating the associations between mirtazapine and cancers." (PMID 34131148, 2021). "Regarding DRD4, the expression levels were significantly higher in cancer cells than in normal cell lines." (PMID 34952904, 2021). "Indeed, numerous studies have provided evidence of the oncogenic roles of MYH9 and DRD4 and suggested these two genes as potential therapeutic targets in diverse cancers." (PMID 36345155, 2023). "DRD4 might regulate chemosensitivity of cancer via inhibiting ferroptosis." (PMID 34906147, 2021). "The results showed that ALOX12, ANGPTL7, DRD4, and MAPK9 remarkably decreased within ESCC samples relative to non-carcinoma samples, whereas SLC38A1 and ZNF419 were highly expressed." (PMID 34291083, 2021). "Besides, methylation of DRD4, ZNF132 and ZNF43 have been reported to play roles in other cancer types." (PMID 35313869, 2022).
neurological disorder (3 papers, 2016 to 2025). "This association remained unchanged after gender; consumption of milk, meat, fruits, and vegetables; parental education level; maternal alcohol consumption during pregnancy; family history of nervous system disease; and DRD4 genetic variations in rs752306 were controlled." (PMID 27384573, 2016). "The functional and pharmacological significance of dopamine receptor D4 (DRD4) in psychiatric and neurological disorders is well elucidated." (PMID 39679842, 2025).
movement disorder (1 paper, 2012). Neurological conditions resulting in abnormal voluntary or involuntary movement, which may impact the speed, fluency, quality and ease of movement. "In a population with chronic mental illness, various tag SNPs in 7 candidate genes (GRIN2B, GRIN2A, HSPG2, DRD3, DRD4, HTR2C, and NQO1) reached nominally significant (p≤0.05) associations with drug-induced movement disorders." (PMID 23226551, 2012).
neurodevelopmental disorder (1 paper, 2022). A behavioral and cognitive disorder with onset during the developmental period that involves impaired or aberrant development of intellectual, motor, or social functions. "Notably, although these genes have not been demonstrated to be directly associated with ALS in previous studies, NR4A1 and DRD4 are reported in AD, ACSL4 seems to be a biomarker of ferroptosis, and SETD1B is associated with syndromic neurodevelopmental disorder." (PMID 35873477, 2022).
DRD4 also shares sentences with these, for which no sentence is quoted: alcoholism (7 papers); bipolar disorder (5); Alzheimer disease (4); Oppositional defiant disorder (4); autism (3); autism spectrum disorder (2); behavior (2); central nervous system tumors (2); Delusion (2); glioma (2); Parkinson's (2); personality disorder (2); adenocarcinoma (1); amyotrophic lateral sclerosis (1); Anorexia (1); anorexia nervosa (1); anxiety disorder (1); Arrhythmia (1); atherosclerosis (1); Bradycardia (1); breast carcinoma (1); bulimia (1); CNS tumors (1); colorectal polyps (1); delirium tremens (1); delusional disorder (1); dysthymia (1); Dystonia (1); emotional dysregulation (1); ependymoma (1).
A further 27 diseases each share a sentence with DRD4 in 1 paper.